MS4A4A (membrane spanning 4-domains A4A)
Description:
May be involved in signal transduction as a component of a multimeric receptor complex.
Synonyms: 4SPAN1; CD20L1; MS4A4; HDCME31P; MS4A7; CD20-L1
Tractability: Antibody: its Gene Ontology location is reachable by antibodies, with high confidence; UniProt predicts a signal peptide or a membrane-spanning region.
Gene: Protein-coding gene on chromosome 11 (60,185,657 to 60,318,080, forward strand). Ensembl gene ENSG00000110079.
Subcellular location: Membrane
Gene Ontology:
Molecular function: protein binding
Cellular component: endoplasmic reticulum; Golgi apparatus; plasma membrane; plasma membrane raft; membrane
Genetic constraint (gnomAD): Loss-of-function variants: 19 observed, 20.55 expected, observed/expected ratio (o/e) 0.92, 90% interval 0.64 to 1.36. The upper end of that interval is the gene's LOEUF score, 1.36, which puts it in group 5 of 6, group 1 being the genes least tolerant of losing a copy. Missense variants: 210 observed, 224.58 expected, observed/expected ratio (o/e) 0.94, 90% interval 0.83 to 1.05. Synonymous variants: 61 observed, 77.29 expected, observed/expected ratio (o/e) 0.79, 90% interval 0.64 to 0.98.
Homologues: Orthologues: chimpanzee MS4A4A (99% identical), macaque MS4A4A (82% identical), mouse Ms4a4a (56% identical), rat Ms4a4a (53% identical). Paralogues in human: MS4A4E (52% identical), MS4A15 (26% identical), MS4A8 (26% identical), MS4A2 (25% identical), MS4A12 (25% identical), MS4A14 (23% identical), MS4A6A (23% identical), MS4A7 (23% identical), MS4A1 (22% identical), MS4A18 (22% identical), MS4A3 (21% identical), MS4A5 (20% identical), and 4 more.
Diseases named in the same sentence as MS4A4A in open-access papers:
MS4A4A is named in the same sentence as 34 diseases in open-access papers, as found by Europe PMC text mining. Sharing a sentence is not in itself a finding about the gene and the disease. The quoted sentences say what the papers report.
Alzheimer disease (6 papers, 2017 to 2025). A progressive, neurodegenerative disease characterized by loss of function and death of nerve cells in several areas of the brain leading to loss of cognitive function such as memory and language. "This agrees with our observation of increased MS4A4A expression being associated with Alzheimer’s disease risk." (PMID 33959712, 2021). "Other genes found to be associated with an increased risk of Alzheimer’s disease in a large genome-wide study are those coding three proteins from the MS4A family (membrane-spanning 4-domains), namely MS4A4A, MS4A4E, and MS4A6E." (PMID 40869138, 2025). "Our TWAS analyses provide evidence that expression of MS4A4A and MS4A6A in CD14+ monocytes is relevant to Alzheimer’s disease risk, although conditional analyses are unable to conclusively localise the signal to either of these genes." (PMID 33959712, 2021). "LACTB2 and PLIN2 had novel significant associations with Alzheimer’s disease and BIN1, PTK2B, SPI1, MS4A4A, MS4A6E, APOE and PVR are in known Alzheimer’s disease risk loci from GWAS." (PMID 33959712, 2021). "This study has unveiled significant new insights into the role of MS4A4A in Alzheimer's disease‐related epilepsy, highlighting its impact on microglial phagocytosis, mitochondrial metabolism, and cytoskeleton, and demonstrating its therapeutic potential in epilepsy management." (PMID 40349168, 2025). "We have shown an association between an increase in expression of MS4A4A and MS4A6A in naïve CD14+ monocytes and Alzheimer’s disease, whereas, after induction with in LPS-induced monocytes, a decrease in gene expression of MS4A4E is associated with Alzheimer’s disease." (PMID 33959712, 2021). "The functional role of MS4A4A was discussed in the pathogenesis of Alzheimer’s disease with no publications linking Ms4a4a gene with voiding dysfunction or MS pathology." (PMID 36490282, 2022). "Although the precise role of MS4A4A, MS4A4E, and MS4A6E in Alzheimer’s disease is still under investigation, current evidence suggests that genetic variations in these proteins may affect immune function and microglial activity in the brain—key elements in the development of Alzheimer’s." (PMID 40869138, 2025).
gastric cancer (5 papers, 2019 to 2022). A primary or metastatic malignant neoplasm involving the stomach. "In this study, MS4A4A was identified as an unfavorable gene associated with poor prognosis in gastric cancer." (PMID 31781506, 2019).
glioma (4 papers, 2022 to 2024). A benign or malignant brain and spinal cord tumor that arises from glial cells (astrocytes, oligodendrocytes, ependymal cells). "While macrophages decrease progressively in different stages of glioma development, the high expression of MS4A4A is associated with adverse survival outcomes in glioma patients." (PMID 38997808, 2024). "In conclusion, MS4A4A exhibits high expression in the GBM‐associated macrophages of glioma patients resistant to PD‐1 immunotherapy, and is correlated with poor prognosis." (PMID 38997808, 2024). "This study proposes a strategy to inhibit MS4A4A to enhance the immune microenvironment in gliomas and improve the efficacy of anti‐PD‐1 immunotherapy, offering new hope for the clinical translation of immune therapy for gliomas." (PMID 38997808, 2024). "This study presents preliminary evidence for MS4A4A as a potential target for immune therapy in gliomas, but its clinical translational prospects require further research and clinical validation." (PMID 38997808, 2024). "Future focus should prioritize preclinical models and in vitro studies to gain a better understanding of the therapeutic potential of inhibiting MS4A4A in human gliomas." (PMID 38997808, 2024). "The genes analyzed included HLA‐DQA1, HLA‐DQB1, HLA‐DMB, LY86, MS4A7, FOLR2, and MS4A4A in glioma patients." (PMID 38997808, 2024). "Subsequently, we injected CT2A and GL261 glioma cells into MS4A4A knockout mice to further explore the influence of MS4A4A on tumor growth." (PMID 38997808, 2024). "Single‐cell sequencing has revealed that M2 macrophages in glioma tissue highly express MS4A4A, and its expression is positively correlated with the expression of immune‐suppressive genes." (PMID 38997808, 2024). "However, there is still a relatively limited amount of research on regulating macrophage function by MS4A4A in gliomas." (PMID 38997808, 2024). "The research underscores MS4A4A as a potential target for immune therapy in gliomas." (PMID 38997808, 2024). "In conclusion, MS4A4A, MS4A4E, MS4A6A, MS4A7, TMEM176A, and TMEM176B may act as potential diagnostic or prognostic biomarkers in glioma and play a role in forming the immune microenvironment in gliomas." (PMID 35734424, 2022). "In TCGA data, the expression level of MS4A4A, MS4A4E, MS4A6A, MS4A7, TMEM176A, and TMEM176B in IDH wild-type glioma was elevated." (PMID 35734424, 2022). "Using bioinformatics analysis methods based on the data from public databases, we found that the expression of MS4A4A, MS4A4E, MS4A6A, MS4A7, TMEM176A, and TMEM176B was significantly overexpressed in glioma tissues compared with that of normal tissues." (PMID 35734424, 2022). "Therefore, these preliminary results indicate that MS4A4A, MS4A4E, MS4A6A, MS4A7, TMEM176A, and TMEM176B are potential prognostic factors for glioma." (PMID 35734424, 2022). "In TCGA data, the expression level of MS4A4A, MS4A4E, MS4A6A, MS4A7, TMEM176A, and TMEM176B in 1p/19q non-codel glioma was elevated." (PMID 35734424, 2022).
COVID-19 (3 papers, 2022). A disease caused by infection with severe acute respiratory syndrome coronavirus 2. "Specifically, we identified three markers, apolipoprotein E (APOE), membrane-spanning 4-domain subfamily A member 4A (MS4A4A), and protein-tyrosine kinase 2-beta (PTK2B), which displayed the same trend in AD and COVID-19 compared to the control group according to our AD-high-risk scores." (PMID 36211330, 2022).
ovarian carcinoma (3 papers, 2020 to 2022). A malignant neoplasm originating from the surface ovarian epithelium. "As a signature of M2-polarized macrophages, MS4A4A is believed to be unfavorable and is involved in several cancers, including gastric, melanoma, and ovarian cancer." (PMID 35493303, 2022). "CD163, MS4A4A and MS4A6A are surface markers for M2 macrophages, and higher MS4A4A and MS4A6A levels were associated with a poorer prognosis in ovarian cancer patients." (PMID 33323552, 2020).
glioblastoma (2 papers, 2021 to 2024). The most malignant astrocytic tumor (WHO grade IV). "In vivo experiments confirm that inhibition of MS4A4A enhances the response of glioblastoma to PD‐1 immunotherapy." (PMID 38997808, 2024). "Moreover, we confirmed the negative prognosis associated with macrophages IHC staining for the macrophage marker MS4A4A in 12 glioblastoma samples, including six from short-term-survival and six from long-term-survival patients." (PMID 34603399, 2021).
rheumatoid arthritis (2 papers, 2022). A chronic, systemic autoimmune disorder characterized by inflammation in the synovial membranes and articular surfaces. "MS4A4A was considered a marker of macrophages and has been associated with autoimmune conditions, such as rheumatoid arthritis, cutaneous systemic sclerosis, polyangiitis, and Kawasaki disease." (PMID 35734424, 2022). "Consistently with in vitro findings, MS4A4A and MS4A7 were expressed in tissue Mφs from COVID‐19 and rheumatoid arthritis patients." (PMID 34346525, 2022).
Sepsis (2 papers, 2017 to 2022). Sepsis is defined as life-threatening organ dysfunction caused by a dysregulated host response to infection. "Among those novel hub genes, we assessed the expression patterns of MYBL1, KLRG1, STOM and MS4A4A from the top 2 sepsis-associated modules (module “midnight blue” and module “cyan”) by qPCR." (PMID 29237456, 2017). "In this study, ROC analysis results further indicate that the four hub genes (MYBL1, KLRG1, STOM and MS4A4A) had good diagnostic performance in sepsis, close to that of genes previously reported." (PMID 29237456, 2017). "Both the qPCR results and ROC analysis results suggest that the four hub genes (MYBL1, KLRG1, STOM and MS4A4A) could be novel diagnostic biomarkers for pediatric sepsis." (PMID 29237456, 2017). "While STOM and MS4A4A were significantly overexpressed in sepsis samples, compared with controls (P = 0.04 and P < 0.001 respectively)." (PMID 29237456, 2017). "qPCR results suggest hub genes (MYBL1, KLRG1, STOM and MS4A4A) in the candidate modules as promising potential transcriptomic markers for pediatric sepsis diagnosis." (PMID 29237456, 2017).
autoimmune disease (1 paper, 2022). A disorder resulting from loss of function or tissue destruction of an organ or multiple organs, arising from humoral or cellular immune responses of the individual to their own tissue constituents. "Specific functions have been described for 3 members of the family (MS4A1/CD20; MS4A2; MS4A4A) and MS4A1/CD20 has proven to be an invaluable therapeutic target for the treatment of B cell malignancies and autoimmune diseases." (PMID 34346525, 2022).
delirium (1 paper, 2026). A disorder characterized by confusion; inattentiveness; disorientation; illusions; hallucinations; agitation; and in some instances autonomic nervous system overactivity. "Nonetheless, our findings suggest newly identified genes (for example MS4A4A, CR1 and TOMM40) that may be of relevance to future delirium research and therapeutic targets investigations." (PMID 41286463, 2026).
epilepsy (1 paper, 2025). A brain disorder characterized by episodes of abnormally increased neuronal discharge resulting in transient episodes of sensory or motor neurological dysfunction, or psychic dysfunction. "In conclusion, our study has uncovered a potential link between AD and MS4A4A likely mediated through its association with epilepsy, suggesting that MS4A4A may play a protective role in the onset of epilepsy." (PMID 40349168, 2025). "Collectively, the results support that the correlation between MS4A4A and AD was due to the contribution of MS4A4A to epilepsy." (PMID 40349168, 2025). "Development of diagnostic tools, biomarkers or intervention strategy based on Ms4a4a is expected in AD or epilepsy pathology." (PMID 40349168, 2025). "Our findings indicate that MS4A4A is upregulated in microglia in AD mouse models, mice with epilepsy and epileptic patients, suggesting its relevance to seizure activity." (PMID 40349168, 2025). "This disruption is magnified in the pathogenesis of epilepsy, as evidenced by the increased incidence of fatal seizures and reduced survival rate in APP/PS1 mice deficient in Ms4a4a." (PMID 40349168, 2025). "In contrast, mice with only the deletion of Ms4a4a did not exhibit epileptic activity, which prompts further investigation into the precise role of Ms4a4a in epilepsy initiation and progression." (PMID 40349168, 2025). "In summary, a significant elevation of MS4A4A expression has been observed in brain lesions of epilepsy patients with diverse etiologies, including FEAT, FCD_2b, and TSC mutations." (PMID 40349168, 2025). "MS4A4A is significantly upregulated in brain lesions in patients with epilepsy." (PMID 40349168, 2025). "The upregulation of MS4A4A in lesion areas may represent a protective mechanism initiated by the body to counteract and balance the progression of epilepsy." (PMID 40349168, 2025). "In addition, we observed an increased expression of MS4A4A in several types of patients with epilepsy." (PMID 40349168, 2025). "Notably, MS4A4A was significantly upregulated across all three epilepsy types." (PMID 40349168, 2025). "Our results revealed a marked upregulation of MS4A4A, MS4A6A, MS4A7, and MS4A14 in lesional tissues of FEAT epilepsy patients relative to perilesional tissues." (PMID 40349168, 2025). "In addition, the absence of MS4A4A has been shown to intensify fatal epilepsy in AD transgenic mice." (PMID 40349168, 2025). "However, given the complexity and intractability of pathological process of epilepsy, these protective mechanisms, including the upregulation of MS4A4A, may only slow disease progression rather than halt it entirely." (PMID 40349168, 2025).
esophageal cancer (1 paper, 2022). A primary or metastatic malignant neoplasm involving the esophagus. "High levels of ANGPT2, FOS, and MS4A4A were correlated with poor prognosis of esophageal cancer, while high levels of VCAN were correlated with better prognosis of esophageal cancer." (PMID 36569220, 2022). "We found that compared with normal human esophageal tissues, ANGPT2, VCAN, and FOS were significantly upregulated in esophageal cancer tissues, MS4A4A was significantly downregulated in esophageal cancer." (PMID 36569220, 2022). "In this study, we found that MS4A4A was a hub gene in esophageal cancer with poor prognosis." (PMID 36569220, 2022). "Thus, VCAN and MS4A4A also participated the effect of neutrophils in esophageal cancer." (PMID 36569220, 2022). "Among 182 genes, four genes including ANGPT2, VCAN, MS4A4A, and FOS had significant prognostic value in esophageal cancer." (PMID 36569220, 2022). "Four genes including ANGPT2, VCAN, MS4A4A, and FOS were considered to have significant prognostic value in esophageal cancer." (PMID 36569220, 2022). "Thus, MS4A4A might influence the progression of esophageal cancer by regulating DCs function." (PMID 36569220, 2022). "High levels of ANGPT2, FOS, and MS4A4A were correlated with poor prognosis of esophageal cancer, while high level of VCAN was correlated with better prognosis of esophageal cancer." (PMID 36569220, 2022). "Thus, FOS and MS4A4A might participate in the function of macrophages in esophageal cancer." (PMID 36569220, 2022). "In the total 182 hub genes, four hub genes including ANGPT2, VCAN, MS4A4A, and FOS had significant prognostic value in esophageal cancer." (PMID 36569220, 2022). "Next, we analyzed the expression of these four important genes (VCAN, ANGPT2, MS4A4A, and FOS) between esophageal cancer and normal esophageal tissues." (PMID 36569220, 2022). "Thus, we considered that hub genes including ANGPT2, VCAN, MS4A4A, and FOS were involved in the pathogenesis of esophageal cancer." (PMID 36569220, 2022).
head and neck squamous cell carcinoma (1 paper, 2021). A squamous cell carcinoma that arises from any of the following anatomic sites: lip and oral cavity, nasal cavity, paranasal sinuses, pharynx, larynx, and salivary glands. "Importantly, GPX4 expression was positively correlated with the expression levels of monocyte markers (CD14 and CD115) and M2 macrophage markers (VSIG4 and MS4A4A) both in ESCA and in head and neck squamous cell carcinoma (HNSC)." (PMID 34722530, 2021).
kidney damage (1 paper, 2023). "The BLNK, MS4A4A, and COL15A1 were all negatively correlated with eGFR, indicating that these genes may aggravate kidney damage in patients with DN." (PMID 36765416, 2023).
osteosarcoma (1 paper, 2022). A usually aggressive malignant bone-forming mesenchymal neoplasm, predominantly affecting adolescents and young adults. "However, IL1B_TAM and FCN1_TAM cells also positively expressed the M2‐TAM signature genes, including MRC1, CD206, MS4A4A and IL4I1, suggesting that they were undergoing the transition into M2‐TAM in osteosarcoma TME." (PMID 36305631, 2022).
pulmonary fibrosis (1 paper, 2024). Chronic progressive interstitial lung disorder characterized by the replacement of the lung tissue by connective tissue, leading to progressive dyspnea, respiratory failure, or right heart failure. "In vivo animal experiments further supported that inhibiting MS4A4A expression mitigated lung fibrosis." (PMID 39457694, 2024). "Furthermore, in vivo experiments demonstrated that inhibiting MS4A4A expression ameliorates lung fibrosis, suggesting that MS4A4A is a promising therapeutic target." (PMID 39457694, 2024).
systemic lupus erythematosus (1 paper, 2024). An autoimmune multi-organ disease typically associated with vasculopathy and autoantibody production. "Some researchers believe that VaD may be linked to systemic autoimmune diseases, and through bioinformatics and ML methods, genes such as C1QA, CD163, LY96, and MS4A4A have been identified as potential biomarkers for the link between VaD and systemic lupus erythematosus." (PMID 39116438, 2024).